WNT7B (Wnt family member 7B)
Diseases named in the same sentence as WNT7B in open-access papers (continued):
Sharing a sentence is not in itself a finding about the gene and the disease.
rheumatoid arthritis (3 papers, 2013 to 2022). A chronic, systemic autoimmune disorder characterized by inflammation in the synovial membranes and articular surfaces. "Increased Wnt7b gene expression has also been reported in the cartilage of patients with osteoarthritis (OA) and rheumatoid arthritis (RA)." (PMID 23360510, 2013). "In contrast to negative regulators of the canonical Wnt-pathway, aberrant expression of Wnts such as Wnt5a and Wnt7B that activate the non-canonical pathway was observed in the joints of rheumatoid arthritis patients." (PMID 27833613, 2016). "Non-canonical Wnt ligands Wnt5a and Wnt7b were upregulated in the joints of rheumatoid arthritis patients, and the non-canonical Wnt/Ca2+ pathway has been associated with the pathophysiology of psoriasis." (PMID 27833613, 2016).
sarcoma (3 papers, 2022 to 2025). A usually aggressive malignant neoplasm of the soft tissue or bone. "Another study identified the up-regulation of MMP13 and WNT7B (which influence oncogenesis) in undifferentiated pleomorphic sarcomas, their presence suggesting the poor differentiation of this subtype." (PMID 40981124, 2025). "WNT7B is a member of the WNT gene family whose altered signaling has been already related with oncogenesis in sarcomas." (PMID 37108089, 2023). "Studies have shown that WNT7B, CA9, MMP13, and RAC3 are associated with poor outcomes in sarcomas." (PMID 36428766, 2022).
asthma (2 papers, 2019 to 2022). "Differential DNA methylation of the same KALRN and WNT7B associated regions were not identified in airway epithelial cells isolated from individuals with and without asthma via pronase digestion (E respectively)." (PMID 31595000, 2019). "For the WNT7B associated region the maximum Δβ of 0.66 was at cg22413388 and signified a decrease in methylation of 66% at cg22413388 in airway epithelial cells isolated from individuals with asthma versus those without asthma, as validated by pyrosequencing." (PMID 31595000, 2019). "In particular, two regions associated with the KALRN and WNT7B promoters had a difference in DNA methylation between airway epithelial cells isolated from individuals with asthma versus those without asthma of greater than 40% (mean Δβ 0.46 and 0.45 respectively)." (PMID 31595000, 2019). "The mean difference in methylation between airway epithelial cells isolated from individuals with asthma versus those without asthma across the WNT7B region of 1167 bp and including five array CpGs was 45%." (PMID 31595000, 2019). "The genes associated with the largest difference in DNA methylation between cells isolated from individuals with asthma versus those without asthma (pronase, DUSP22; bronchial brush, WNT7B) have links to asthma pathogenesis." (PMID 31595000, 2019).
bladder cancer (2 papers, 1998 to 2021). "The expression of one transforming (Wnt7b) and one non-transforming (Wnt5a) Wnt gene in four human bladder carcinoma cell lines, and in normal human bladder tissues (n = 8) and bladder cancers (n = 48) were analysed by ribonuclease protection analysis." (PMID 9461004, 1998).
cholangiocarcinoma (2 papers, 2022 to 2024). A carcinoma that arises from the intrahepatic biliary tree (intrahepatic cholangiocarcinoma) or from the junction, or adjacent to the junction, of the right and left hepatic ducts (hilar cholangiocarcinoma). "Increased transcription of Wnt ligands, especially Wnt7b, is mainly due to secretion by macrophages in cholangiocarcinoma." (PMID 36209344, 2022). "In cholangiocarcinoma (BDC), DRD1 acts as a key protein involved in the proliferation of autonomous cancer stem cell‐like cells (CSCs) by regulating endogenous Wnt Family Member 7B (WNT7B)." (PMID 38494840, 2024).
head and neck squamous cell carcinoma (2 papers, 2018 to 2022). A squamous cell carcinoma that arises from any of the following anatomic sites: lip and oral cavity, nasal cavity, paranasal sinuses, pharynx, larynx, and salivary glands. "DACT, WNT5A, and WNT7B were significantly positive correlation with TET1(p < 0.05), and WNT4 and WNT7A were negative correlation with TET1 in the TCGA Head and Neck Squamous cell Carcinoma database (p < 0.05)." (PMID 30075814, 2018).
ischemic stroke (2 papers, 2025 to 2026). A stroke disorder caused by obstruction of blood flow to the brain, due to thrombotic (local blood clot formation) or embolic (due to a blood clot or other material traveling from another site) event. "After successfully establishing the optogenetic mouse model, we assessed the proportion of Wnt7b+ astrocytes on Day 7 following ischemic stroke." (PMID 41346705, 2026). "We found that a Piezo1-Ca2+-mediated increase in the proportion of Wnt7b+ astrocytes can regulate glial scar stiffness, which directs the NSC lineage choice during regeneration after ischemic stroke." (PMID 41346705, 2026). "Therefore, we performed a proteomic analysis of Wnt7b+ fibrotic and Wnt7b- astrocytes in the peri-infarct area using LCM-MTA, considering their spatiotemporal distribution patterns prior to and after ischemic stroke." (PMID 41346705, 2026). "In contrast, however, we also observed upregulation of Wnt7b, another canonical Wnt ligand secreted by astrocytes with critical roles in astrocytic development, maintaining the BBB integrity, and BBB repair after ischemic stroke." (PMID 41156605, 2025).
lung adenocarcinoma (2 papers, 2019 to 2025). A carcinoma that arises from the lung and is characterized by the presence of malignant glandular epithelial cells. "WNT7B is a clear cancer-related gene, and its expression was significantly upregulated in lung adenocarcinoma tumors in the TCGA database." (PMID 41184502, 2025). "In order to find supporting evidence in clinical samples for our model, we searched the expression data for GATA4, TGFB2, and WNT7B in lung adenocarcinoma patients from The Cancer Genome Atlas (TCGA)." (PMID 30971692, 2019). "Aberrant hypermethylation of cancer transcriptional regions leads to overexpression of related genes, which could explain the elevated expression of WNT7B in lung adenocarcinoma and suggests that this gene is most likely also upregulated in adjacent tissues surrounding the tumor." (PMID 41184502, 2025).
multiple myeloma (2 papers, 2022 to 2024). "Previous studies have demonstrated that in multiple myeloma, IDH2 enhances the expression of WNT7B and activates the WNT signaling pathway by targeting the m6A demethylase FTO, thereby promoting the occurrence and development of multiple myeloma." (PMID 39641872, 2024). "In multiple myeloma, IDH2-mediated FTO activation could reduce the m6A level on WNT7B transcripts, thereby elevating WNT7B expression and thus activating Wnt signaling crosstalk." (PMID 35945194, 2022).
osteoarthritis (2 papers, 2013 to 2023). A noninflammatory degenerative joint disease occurring chiefly in older persons, characterized by degeneration of the articular cartilage, hypertrophy of bone at the margins and changes in the synovial membrane. "The secretome profile analysis revealed that two genes (WNT7B and WNT9A) from the Wnt-signaling pathway, which is implicated in osteoarthritis development, were only up-regulated for female donors." (PMID 36658138, 2023).
skin tumors (2 papers, 2019 to 2020). "Microsatellite analyses indicate that the skin cancer phenotype is linked to a 20 Mb region of 129P2 chromosome 15 harbouring the Wnt7b gene." (PMID 30926782, 2019). "A similar dependence on Wnt7b is found for the migratory activity of the skin tumour cell clones as Wnt7b inactivation impairs the migration of tumour cells in a conventional scratch assay." (PMID 30926782, 2019). "All together, these results indicate that in the chr15: 67–87 Mb region Wnt7b is a critical gene for the transformation of Cdkn2ab−/− skin tumour cells at least in vitro." (PMID 30926782, 2019). "Overexpression of CDK6 by retroviral transduction results in very efficient soft agar colony outgrowth both of skin tumour cell lines, with or without inactivation of the endogenous Wnt7b allele, and Cdkn2ab KO MEFs." (PMID 30926782, 2019). "Since the amino acid sequences of both PDGFβ and WNT7b encoded by FVB/N and 129P2 genes are identical this suggests that variation in their regulatory sequences or post-transcriptional mRNA stability underlies the enhanced expression of the 129P2 alleles in the skin tumours." (PMID 30926782, 2019). "Therefore, we disrupted the Wnt7b gene in skin tumour cells using CRISPR/Cas9 technology." (PMID 30926782, 2019).
acute lymphoblastic leukemia (1 paper, 2020). Leukemia with an acute onset, characterized by the presence of lymphoblasts in the bone marrow and the peripheral blood. "Other Wnts such as Wnt4, Wnt5B, Wnt6, Wnt7B, Wnt9A, Wnt10A, Wnt14, and Wnt16 are robustly expressed in CLL B-cells and acute lymphoblastic leukemia (ALL) cells, whereas these can be scarcely detected in normal pre-B cells." (PMID 33126517, 2020).
atherosclerosis (1 paper, 2026). A disease characterized by the build-up of fatty material and calcium deposition in the arterial wall resulting in partial or complete occlusion of the arterial lumen. "The KEGG enrichment analysis revealed that Wnt7b+ astrocytes exhibited an increased expression of proteins associated with fluid shear stress, atherosclerosis, and the cAMP signaling pathway." (PMID 41346705, 2026).
attention deficit-hyperactivity disorder (1 paper, 2024). A disorder characterized by a marked pattern of inattention and/or hyperactivity-impulsivity that is inconsistent with developmental level and clearly interferes with functioning in at least two settings (e.g. at home and at school). "Impairment in the Wnt pathway has been associated with various psychiatric disorders in humans, such as WNT1, WNT2, and WNT7A in autism spectrum disorder, WNT7B and LRP5 in SCZ, and LRP5 and LRP6 in attention-deficit/hyperactivity disorder." (PMID 39452096, 2024).
bladder tumours (1 paper, 1998). "Wnt5a and Wnt7b mRNAs were both expressed in normal bladder tissues and bladder tumours." (PMID 9461004, 1998).
bone sarcoma (1 paper, 2015). A sarcoma that arises from the bone. "Clearly, further studies are needed to determine the primary function of Wnt6, Wnt7b and Wnt11 in bone sarcomas." (PMID 25999350, 2015). "In contrast, among noncanonical Wnt ligands, the expression of Wnt5a, Wnt5b and Wnt16 was either decreased or lost in bone sarcoma cells; however, Wnt6, Wnt7b, and Wnt11 were remarkably increased in bone sarcoma cells." (PMID 25999350, 2015). "In contrast, the noncanonical Wnt6, Wnt7b, and Wnt11 were significantly increased in bone sarcoma cells." (PMID 25999350, 2015).
breast tumors (1 paper, 2025). "Similarly, WNT2 and WNT7B were highly upregulated, whereas WNT11 was highly downregulated in HER2-positive breast tumors compared with that in the control tissue." (PMID 41044153, 2025).
cardiac hypertrophy (1 paper, 2023). "In the current study, WNT7B was identified to be a target of miR-765, and its level was downregulated in Ang II-induced cardiac hypertrophy." (PMID 37197359, 2023). "Overexpression of Mhrt protected against Ang II-induced cardiac hypertrophy via the miR-765/WNT7B axis." (PMID 37197359, 2023). "The goal of the study provided a potential option, mediating the Mhrt/miR-765/WNT7B axis, to treat pathological cardiac hypertrophy." (PMID 37197359, 2023). "Taken together, the downregulation of miR-765 targeted WNT7B to suppress Ang II-induced cardiac hypertrophy." (PMID 37197359, 2023). "Additionally, the knockdown of WNT7B reversed the suppression of myocardial hypertrophy induced by downregulating miR-765." (PMID 37197359, 2023). "In the present study, we explored the function of Mhrt in cardiac hypertrophy and found that Mhrt could alleviate Ang II-induced cardiac hypertrophy via the miR-765/WNT7B pathway." (PMID 37197359, 2023). "Taken together, Mhrt alleviated cardiac hypertrophy by targeting the miR-765/WNT7B axis." (PMID 37197359, 2023). "However, the role of WNT7B in cardiac hypertrophy remains unknown." (PMID 37197359, 2023).
chronic lymphocytic leukaemia (1 paper, 2021). "Wnt members, including Wnt3, Wnt4, Wnt5B, Wnt6, Wnt7B, Wnt9A, Wnt10A, Wnt14 and Wnt16, are highly expressed in chronic lymphocytic leukaemia B cells." (PMID 33417298, 2021).
dental caries (1 paper, 2024). The decay of a tooth, in which it becomes softened, discolored, and/or porous. "As Wnt7b stimulates the proliferation and migration of HDPCs, it has an important role in the treatment of tooth injuries, such as dental trauma and dental caries, as well as in the reservation of vital pulp." (PMID 38995004, 2024).
endometrial carcinoma (1 paper, 2023). A malignant tumor arising from the epithelium that lines the cavity of the uterine body. "For example, the overexpression of WNT-7A exerts pathogenic effects, and the WNT-7A and WNT-7B expression levels were found to be higher in endometrial carcinoma cell lines than in normal primary endometrial cultures." (PMID 37176048, 2023).
gastric tumor (1 paper, 2017). "Suppression of UBE2T also inhibits gastric tumor invasion and metastasis via the WNT signal pathway by inhibiting WNT5A and WNT7B, which in turn promotes GSK3B expression, activates β-Catenin, and inhibits the key oncogene c-Myc." (PMID 28427240, 2017).
glaucoma (1 paper, 2020). Increased pressure in the eyeball due to obstruction of the outflow of aqueous humor. "Results showed that 8 genes were significantly changed, 6 of which were down‐regulated in glaucoma, such as WNT7B and DKK1." (PMID 31680442, 2020).
keratoconus (1 paper, 2026). A degenerative, structural disorder of the eye, characterized by a cone-shaped protrusion of the cornea. "Meanwhile, genes in the Wnt signaling pathway have gained attention: one study found that polymorphisms in WNT10A and WNT7B were associated with keratoconus and central corneal thickness, dovetailing with transcriptomic evidence of Wnt pathway dysregulation in KC corneas." (PMID 41595486, 2026).
leukoplakia (1 paper, 2025). A white patch or plaque on a mucous membrane that cannot be characterized clinically or pathologically as any other disease. "Among these four Wnt ligands, mRNA levels of Wnt3a, Wnt5b and Wnt7b are upregulated in leukoplakia and early stage OSCC, suggesting that if a causality is determined between periodontitis and OSCC, these ligands may participate in initiating malignant transformation of normal oral cells." (PMID 40421179, 2025). "Our transcriptomic analysis of the GEO database (GSE85195) shows that Wnt7a and Wnt7b mRNA levels are significantly increased in leukoplakia and early stage OSCC." (PMID 40421179, 2025).
liver cancer (1 paper, 2023). An epithelial or non-epithelial malignant neoplasm that arises from the liver. "Recent studies link Wnt9A polymorphism to HCC risk, Wnt7B to sorafenib resistance, and DVL1 to Wnt activation and poor prognosis liver cancer." (PMID 38036507, 2023).
liver fibrosis (1 paper, 2023). "Moreover, FN1, COL1, and iNOS axis-mediated liver fibrosis were caused by DOX, and our data documented the fibrotic effect of DOX via the upregulation of VEGF, Wnt7b, β-catenin, FN1, Col-1, TGFβ1, iNos, and Bax in the DOX group." (PMID 37296647, 2023).
lymphoma (1 paper, 2020). A malignant (clonal) proliferation of B- lymphocytes or T- lymphocytes which involves the lymph nodes, bone marrow and/or extranodal sites. "According to this analysis, the Wnt7b TAD boundary lies immediately upstream of the Wnt7b TSS in both HMECs and mouse lymphoma cells." (PMID 33625717, 2020).
malignant glioma (1 paper, 2016). A grade III or grade IV glioma arising from the central nervous system. "Thus, molecules that are generally associated to repulsive clues, such as Slit2–3 and Shh, appeared to be downregulated, whereas attractors such as Wnt7b and Vegfa were upregulated, consistently with the acquisition of the infiltrating capacity that characterizes malignant gliomas." (PMID 26923714, 2016).
metastatic prostate carcinoma (1 paper, 2023). A carcinoma that arises from the prostate gland and has spread to other anatomic sites. "WNT7B, WNT9A and WNT10B were all increased in metastatic prostate cancer, compared to the normal prostate." (PMID 37373067, 2023). "Indeed, in the GEO datasets presented here (GSE6919 and GDS1439), WNT7B, WNT9A and WNT10B were all increased in metastatic prostate cancer, where PHB levels were reduced." (PMID 37373067, 2023).
nasal polyp (1 paper, 2024). "Consistent with a prior report identifying higher expression of WNT7B in nasal polyp tissue compared with donor-matched inferior turbinate tissue, we observed high expression of WNT7B in nasal polyp basal EpCs." (PMID 38444858, 2024).
nutritional deficiency (1 paper, 2022). "However, WNT7B was suggested to improve the tolerance of cells to nutritional deficiency, as WNT7B knockdown cells recovery from cell cycle synchronization more slowly than the control." (PMID 35850748, 2022).
Obesity (1 paper, 2024). Accumulation of substantial excess body fat. "As high-fat feeding leads to obesity and systemic metabolic dysregulation, here we investigate the potential benefit of Wnt7b overexpression in osteoblasts on both bone and whole-body metabolism in mice fed with a high-fat diet (HFD)." (PMID 39434845, 2024). "As Wnt proteins function predominantly in an autocrine or paracrine manner, Wnt7b-induced bone anabolism instead of Wnt7b per se was likely responsible for the apparent anti-obesity effect." (PMID 39434845, 2024).
oral lichen planus (1 paper, 2022). Oral lichen planus is a chronic inflammatory oral condition of unknown aetiology characterized by T-cell-mediated chronic immune response and abnormal epithelial keratinization cycle. "Among these OSCC positive WNTs, only WNT7B was progressively increased in normal, OLP (oral lichen planus), and OSCC tissues in both patients." (PMID 35850748, 2022).
osteosclerosis (1 paper, 2021). Abnormally high bone density. "As previous studies have shown that Bmpr1a deletion increases preosteoblast proliferation as a main cause for osteosclerosis, we set out to determine whether Wnt7b has a similar effect by performing EdU labeling experiments." (PMID 34031510, 2021).
pancreatic ductal adenocarcinoma (1 paper, 2026). An infiltrating adenocarcinoma that arises from the epithelial cells of the pancreas. "In pancreatic ductal adenocarcinoma (PDAC), elevated WNT7B and WNT10A correlate with aggressive, basal-like disease and poor patient survival, but the mechanisms underlying this association remain unclear." (PMID 41797924, 2026).
periodontitis (1 paper, 2025). An acute or chronic inflammatory process that affects the tissues that surround and support the teeth. "Together, it was found that Wnt ligands Wnt3, Wnt3a, Wnt5b and Wnt7b are concomitantly upregulated in periodontitis and oral carcinogenesis." (PMID 40421179, 2025). "By analyzing the GEO databases GSE223924 and GSE85195 we found that the Wnt ligands Wnt3, Wnt3a, Wnt5b and Wnt7b are transcriptionally upregulated in periodontitis and OSCC, especially during early carcinogenic phases." (PMID 40421179, 2025). "Interestingly, the transcriptional upregulation of Wnt3, Wnt3a, Wnt5b and Wnt7b in periodontitis (GSE223924) was also observed in oral carcinogenesis (GSE85195)." (PMID 40421179, 2025). "Transcriptomic Z-score analysis shows that among 19 Wnt ligands available, two canonical Wnt ligands (Wnt3 and Wnt3a) and two non-canonical Wnt ligands (Wnt5b and Wnt7b) are upregulated in periodontitis." (PMID 40421179, 2025).